ANP32CP (acidic nuclear phosphoprotein 32 family member C, pseudogene)
Synonyms: PP32R1; formerly ANP32C
Gene: Processed pseudogene on chromosome 4 (164,197,007 to 164,197,711, reverse strand). Ensembl gene ENSG00000248546.
Diseases named in the same sentence as ANP32CP in open-access papers:
ANP32CP is named in the same sentence as 4 diseases in open-access papers, as found by Europe PMC text mining. Sharing a sentence is not in itself a finding about the gene and the disease.
ANP32CP shares sentences with these, for which no sentence is quoted: breast carcinoma (2 papers); cancer (2); pancreatic tumours (1); tumor (1).